IL4 (interleukin 4)
Diseases named in the same sentence as IL4 in open-access papers (continued):
Sharing a sentence is not in itself a finding about the gene and the disease.
tumor (continued). "In contrast, exposure to IL-4 and/or IL13 (24h) polarizes them towards pro-tumor M2-macrophage fate (aka tumor associated macrophages or TAMs), as detected by increased expression of the M2-macrophage biomarkers; CCL17 and CCL18 in them (see RT/PCR analysis)." (PMID 29262555, 2017). "Tumor derived molecules, such as IL-4, IL-10, and transforming growth factor-β1 (TGF-β1), have been proposed as major factors inducing M2-polariziation of TAMs." (PMID 28032600, 2017). "To explore potential mechanism(s) of IL-4-related tumor cell proliferation further, we examined the effect of IL-4 on the expression of the two known isoforms of NOX1, NOX1-L and NOX1-S." (PMID 28498822, 2017). "Tumor cells produce cytokines responsible for the recruitment and polarization of macrophages to M2 profile such as IL-4, IL-10, IL-13, and TGF-β, as well as chemokines such as CCL2 (MCP-1), CCL3, and CCL14." (PMID 28970834, 2017). "In pancreatic tumor, IL-4 autocrine origin is essential in the control of normal macrophages transition into tumor-promoting macrophages." (PMID 28927416, 2017). "Cytokines, like TNF, IL-1β, IL-4, IL-13, and TGF-β, secreted by medullary cells, can also lead to the mutation of cancer related genes, and thus, the promotion of tumor formation." (PMID 29212288, 2017). "There, we used a Mo-DC vaccine differentiated to iDC by IL-4 and GM-CSF and to mDC by TNFα alone simultaneous to loading with autologous tumor lysate." (PMID 28601925, 2017). "Although tumor antigen-stimulated CD4+ T cells can produce IFN-γ (Th1) or IL-4 (Th2) and both these cytokines can recruit other tumoricidal cells to the tumor site, tumor rejection is mediated by IL-4." (PMID 29250133, 2017). "For examples, IL-4 was reported to promote the growth, angiogenesis, and invasion of tumor cells by inducing cathepsin activity in macrophages." (PMID 27909985, 2017). "Studies showed that when macrophages are exposed to a tumor microenvironment that overexpresses IL-4 and IL-10, the macrophages are polarized and differentiate into M2 macrophages, which are also known as tumor associated macrophages (TAMs)." (PMID 28592924, 2017). "The high levels of IL-4 produced modifies the tumour microenvironment and facilitates an increase in arginase-1 levels, considered a biomarker of TAMs." (PMID 28381274, 2017). "Interleukin-4 plays a critical role in the regulation of immune responses and has been detected at high levels in the tumour microenvironment of cancer patients, where concentrations correlate with the grade of malignancy." (PMID 28553931, 2017). "A major attribute of type II NKT-mediated suppression of tumor immunity is elevated production of IL-13 and IL-4 cytokines capable of skewing the cytokine response predominantly toward tumor-promoting Th2 type." (PMID 29018445, 2017). "Increased NOX1 expression produced by IL-4 exposure in the DLD-1 line, similar to HT-29 cells, was also associated with an increase in tumor cell growth and the production of ROS." (PMID 28498822, 2017). "In concert with these results, exposure of DLD-1 cells to IL-4 primarily increased NOX1-L expression, which was associated with increased tumor cell proliferation and ROS production." (PMID 28498822, 2017). "In the tumor site of action, TAMs produce cytokines such as IL-10, IL-4, and IL-13 that will act to repair tissues and attract other auxiliary cells that can activate TAM and hence, promoting tumor growth." (PMID 28970834, 2017). "On the other hand, L-4F inhibited both the cytokines (IL-4 and IL-17A) producing cells in tumor tissues and the important signaling molecules (phosphorylation of ERK and STAT3)." (PMID 29245934, 2017). "Of the two major macrophage phenotypes (M1 and M2), the M2 phenotype of TAMs in the tumor region are basically regulated by a subset of tumor-secreted factors, such as M-CSF, IL-4, IL-13 and IL-10." (PMID 28032600, 2017).
tumor (continued). "In fact, even in a Th2‐M2 tumour microenvironment macrophages stimulated by IL‐4 and IL‐13 were able to inhibit proliferation of B16‐F1 melanoma cells." (PMID 28032353, 2017). "Because stable NOX1 knockdown in HT-29 cells significantly decreases tumor cell proliferation, we examined the effect of IL-4 exposure on the growth of parental HT-29 cells and NOX1 knockdown clonal variants." (PMID 28498822, 2017). "An additional recent system developed by Mohammed and colleagues for the treatment of prostate cancer, a tumor characterized by elevated IL-4 levels, consists in an inverted cytokine receptor (ICR)." (PMID 28331617, 2017). "In this model, human monocytes separated from the peripheral blood of healthy donors were cultured with GM-CSF and IL-4 in the presence of sera from tumour patients or their healthy donor counterparts." (PMID 28350008, 2017). "DC exosomes pulsed with tumor peptides (GM-CSF and IL-4) were also employed in vivo, which resulted in suppression or eradication of the established tumor." (PMID 28538671, 2017). "Cumulatively, these results suggest that IR-induced IL-4 regulates tumor progression by promoting β-catenin/Stat6 via activation of JAK and JNK." (PMID 27895317, 2016). "Human tumor cell lines including expressing IL-4R has been shown to mediate anti-proliferative activity of IL-4." (PMID 26993600, 2016). "We next used recombinant IL-4 and anti-IL-4 antibody to evaluate the signaling mechanism by which IL-4 mediates IR-induced tumor progression in human carcinomas." (PMID 27895317, 2016). "In response to polarization signals, such as IL-4, IL-13, transforming growth factor-β, and matrix metalloproteinase-9, monocytes in the tumor polarize into M2 macrophages." (PMID 27129159, 2016). "While spleen cells of both control mice and vaccinated mice produced increased levels of IL-4 in the presence of the tumor-conditioned medium, the amount produced was less than that seen for IFN-γ or the inflammatory mediators IL-6 and TNF-α." (PMID 27598146, 2016). "Tumor derived cytokines such as IL-4, IL-10, IL-13, TGFβ and prostaglandin E2 can drive the production of M2 macrophages while IL-12 is produced by M1 macrophages." (PMID 26654940, 2016). "Natural killer T (NKT) cells are a subpopulation of T lymphocytes, which are considered tumor cell killers; they produce antitumor molecules, such as Fas ligand (FasL), IL-4, IFN-γ, IL-13, perforin, and granzyme, that also promote lysis of tumor cells." (PMID 27294132, 2016). "Recently, to investigate the roles of cytokines in CSCs of OSCC, we profiled expression of 25 cytokines and found that IL4 was highly increased in tumor spheres compared to corresponding adherent monolayer cells (manuscript in preparation)." (PMID 27259269, 2016). "The Th2 cytokines IL-4 and IL-10 suppress the generation of CTLs and Th1 cells and recruit tumour entry of Tregs." (PMID 27777963, 2016). "The expansion and activation of MDSCs is regulated by several factors (e.g. IL-4, IL-13, IL-1α, INFγ and GM-CSF) that are released by activated macrophages and T cells, tumor cells, tumor stromal cells, and by pathogen-infected cells." (PMID 27191744, 2016). "To study the tumor microenvironment-related effects of IR on tumor progression and metastasis, we screened for IR-induced cytokines and found that IL-4 mRNA levels were increased dramatically after IR exposure in various cancer cell types." (PMID 27895317, 2016). "Immature neutrophils that are released from BM as a result of tumor-driven emergency myelopoiesis were shown to become activated with cytokines released in tumor microenvironment (GM-CSF, IL-4, TNF-α) and acquire molecular features characteristic for DCs." (PMID 28066438, 2016). "Immunohistochemical analysis showed that the number of IL-4 immunoreactive cells was higher in the tumor tissues of IL-4 mice." (PMID 26993600, 2016). "Following NAC, 43.8% (7 out of 16) of tumour samples showed alteration in the level of expression of IL-4." (PMID 27777963, 2016).
tumor (continued). "IL-1β was abundant in P29 tumours at the mRNA level, particularly in the peripheral region, in B6 mice compared with those tumours in IL-33−/− mice, and IL-4, IL-6 and TRAIL expression was quite low in both types of tumours." (PMID 26775708, 2016). "We also confirmed the role of IL-4 signaling pathway in IR-induced tumor progression using sh-IL4-transfected A498 and MDA-MB-231 cells." (PMID 27895317, 2016). "Type 1 (IFN-γ, IL-12) and type 2 (IL-4, IL-10) cytokines were measured next in supernatants collected from tumour lysate-pulsed DCs co-cultured with syngeneic naїve T-cells." (PMID 26795765, 2016). "Several studies have reported that IL-4 is primarily involved in the promotion of differentiation, proliferation, and survival of epithelial tumor cells through its interaction with IL-4Rα." (PMID 27895317, 2016). "On the other hand, in the presence of cytokines, such as IL-4 and IL-13, macrophages differentiate into immunosuppressive M2-macrophages characterized by IL-10 production that promotes tumor progression." (PMID 27493669, 2016). "Following tumor induction, administration of rIL-33 induced the development of IL-5-producing ILC2, which recruited and maintained eosinophils that induced tumor cell death and prevented tumor metastasis, possibly through an IL-4-dependent mechanism." (PMID 27882334, 2016). "Along with CD8+ and CD4+ T lymphocytes, Th0 subtype of T cells promotes the production of INF-γ and suppresses the secretion of IL-4, contributing to the proliferation of Th1 subtype over Th2 cells in the tumor microenvironment." (PMID 27246873, 2016). "Recently, PGE2 has been implicated in the enhancement of protumorigenic Th2-type cytokine, such as IL-4, IL-5, and IL-10, and inhibition of the anti-tumor Th1 cytokine production, such as IFN-γ and IL-2." (PMID 28053982, 2016). "One of the reported mechanisms for tumor escape is that recruited immune cells express cytokines such as IL-13 and IL-4 to generate a tumor-favoring microenvironment." (PMID 27081854, 2016). "In IL-4 mice, reduced tumor volume and weight were observed when compared with those of non-transgenic mice." (PMID 26993600, 2016). "Human tumor cell lines expressing IL-4R has been shown to mediate anti-proliferative activity of IL-4." (PMID 26993600, 2016). "The major difference seen was an increased level of IL-4 production by unstimulated spleen cells of mock-vaccinated tumor-bearing mice compared to unstimulated spleen cells from the other two groups of mice." (PMID 27598146, 2016). "On the other hand, IL-4 plays a regulatory role on macrophage polarization towards the tumor-promoting phenotype." (PMID 26799669, 2016). "Encapsulated lysate pulsed DCs stimulated T cells of all three patients released variable amounts of IFN-γ and IL-4, compared to tumor lysate alone, stimulation of T cells with NP-lysate-pulsed DCs induced a nonsignificant increase in IFN-γ and IL-4secretions." (PMID 27782834, 2016). "Macrophages, an important cell component of the tumor stroma, are recruited and mobilized by tumor-derived factors such as IL-4, IFN-γ and IL-13 and then induced to differentiate into pro-tumorigenic tumor-associated macrophages (TAMs)." (PMID 27367025, 2016). "Of note, IL-4 has also been shown to inhibit tumor growth and progression in other tissues, such as renal cancer and glioblastoma." (PMID 27148488, 2016). "While IL-13 is protective, IL-4 clearly promotes tumour growth in this model and is mainly produced by the inflammatory infiltrate." (PMID 27357235, 2016). "The results of this study suggest that radiation-induced IL-4 contributes to tumor progression and metastasis." (PMID 27895317, 2016). "Accordingly, IR-induced downregulation of miR-340 and/or miR-429 de-represses IL-4 expression and promotes tumor progression, ultimately making IL-4 to act as a malignancy inducer." (PMID 27895317, 2016).
tumor (continued). "According to previous reports, IL-4 and IL-4Rα expression are increased in several types of tumor cells, suggesting the involvement of IL-4 in tumor progression and metastasis after IR exposure." (PMID 27895317, 2016). "Increased CTSS expression at the tumor site has been reported to be a result of tumor associated macrophage (TAM) recruitment, with the presence of CTSS dependent on IL-4, indicative of an M2 phenotype." (PMID 27097645, 2016). "It was previously reported that IL-4 plays a critical role in the regulation of immune responses and is detected at high levels in the tumor microenvironment of cancer patients, where it is correlated with the grade of malignancy." (PMID 27895317, 2016). "We described that combining radiotherapy with IL-4-inhibiting treatment, including miR-340 and miR-429, decreased IR-induced aggressive tumor behavior." (PMID 27895317, 2016). "A large amount of molecules released by tumor cells or tumor-surrounding cells, including IL-1β, IL-4, IL-6, IL-10, IFN-γ and TGF-β, are reported to re-program immature myeloid cells to become immunosuppressive." (PMID 26967390, 2016). "In this regard, tumor cells have been shown to direct TAM polarization through release of cytokines including IL-4 and TGF-β." (PMID 26918785, 2016). "In our in vitro study we observed typical M1 or M2 polarization patterns in monocyte derived macrophages generated by IFN-γ/LPS or IL-4/IL-13 and a mixed M1/M2 phenotype after polarization with tumour cells." (PMID 25902944, 2015). "In line with the results of Th1 differentiation, combined treatment of anti-IL-4 and anti-IL-21 Abs significantly reversed the impaired induction and function of tumour-specific CD8+ T cells in response to tumour inoculation in aged mice." (PMID 25850032, 2015). "This is consistent with in vitro observations showing that conditioned medium from IL-4 transduced tumor cells activated the Jak-Stat pathway and arginase I expression in the tumor cells." (PMID 27563494, 2015). "This suggests that the role of the IL-4/IL-13 axis in the pro-tumor effects of apoptosis is distinct from the IL-4Rα-dependent, alternative macrophage activation pathway." (PMID 25702581, 2015). "The transcription of GATA3 and the protein level of IL-4 were reduced in the tumour tissue exposed to E-cadherin + DCs relative to that exposed to E-cadherin- DCs." (PMID 25651850, 2015). "Our studies support an inhibitory effect of tumor-derived IL-4 on primary tumor growth, but perhaps even more significantly, they showed a dramatic effect of IL-4 in eliminating distant metastasis." (PMID 27563494, 2015). "Since alternatively activated M2 macrophages are implicated in promoting tumor growth and metastasis, we were surprised to see less aggressive tumor growth in mice engrafted with IL-4 expressing AC2M2 cells." (PMID 27563494, 2015). "In order to gain a broader perspective on the effects of IL-4 on the tumor microenvironment we assessed expression of a panel of 691 immune genes using nanoString-based transcript quantification." (PMID 27563494, 2015). "IL-13 and IL-4 modify the function of macrophages, and IL13RA2 mediates IL13/4 mediated tumor associated macrophage M1/M2-Th1/Th2 phenotype, especially, IL-13 signaling promote to change M1 to M2." (PMID 26114873, 2015). "We also observed that similar to human BCCs, the tumor stroma of murine BCCs show characteristic features of a Th2 microenvironment including increased expression of IL4 and the presence of cells expressing CD4/FOXP3." (PMID 26413810, 2015). "It has been reported that the all-trans retinoic acid (ATRA) and IL-4 induced MDSCs to differentiate into mature myeloid cells and enhanced the efficacy of tumor vaccine." (PMID 26181041, 2015).
tumor (continued). "Exposure of TAM to tumor-derived cytokines such as IL-4, IL-10, IL-13, and M-CSF is able to convert them into polarized type II or M2 macrophages with immune-suppressive activities resulting in tumor progression." (PMID 26441986, 2015). "This study was designed to explore the effect of cancer cell derived IL-4 on the tumor immune stroma and metastasis." (PMID 27563494, 2015). "Transcriptome analysis revealed an immune signature consistent with IL-4 induced M2 polarization of the tumor microenvironment and a generalized increase in myeloid involvement in the tumor stroma." (PMID 27563494, 2015). "Both IL-4 and GM-CSF have shown promise as immune modulatory cargoes in the context of tumor vaccine and oncolytic virus approaches." (PMID 27563494, 2015). "Human peripheral blood monocytes were differentiated into monocyte derived macrophages (MDM) using M-CSF and polarized into M1 by IFN-γ and LPS and into M2 macrophages by IL-4 and IL-13 or by co-culture with two different tumour cell lines." (PMID 25902944, 2015). "Whereas anti-tumor Th1 cells limit tumor progression by enhancing cytotoxic T-cell responses, pro-tumor Th2 cells skew adaptive responses toward humoral immunity via production of cytokines such as IL-4 and IL-10." (PMID 26690220, 2015). "In contrast, alternatively activated (M2) macrophages are induced by T helper type 2 cytokines including interleukin-4 (IL-4), IL-10 and IL-13 and show immunoregulatory, anti-inflammatory and tumor-promoting activity." (PMID 26714314, 2015). "This was supported by flow cytometry analysis which detected ~2 times more F4/80+ macrophages in IL-4 expressing tumor stroma." (PMID 27563494, 2015). "Once in the tumor microenvironment, MDSCs are functionally programmed to be immunosuppressive by the local cytokine profile, with Th2-type cytokines IL-4 and IL-10 driving MDSCs to suppress effector T-cells." (PMID 26690220, 2015). "IL-4 production from cancer cells is expected to have pleotropic effects on the tumor stroma through influencing the recruitment of immune cells and gene expression within immune and other cell types in the tumor microenvironment." (PMID 27563494, 2015). "Although clinical benefit has been documented using this IL-4 DC-based approach, the past decade has witnessed the introduction of several new protocols that enable the generation of DCs with optimized anti-tumor immunostimulatory activity." (PMID 25951230, 2015). "Collectively, these observations argue that cancer cell derived IL-4 can induce M2 macrophage activation in vitro as well as in the tumor microenvironment in vivo." (PMID 27563494, 2015). "After repeated activation, however, these cells become anergic and switch to a cytokine profile that inhibits anti-tumor immune responses and favors tumor progression (i.e., a high ratio of IL-4 to IFN-γ)." (PMID 26695753, 2015). "In melanoma, production of B cells secreting inhibitory IgG4 is stimulated by the tumor secreted IL-10 and IL-4." (PMID 24743024, 2014). "Already 15 years ago CD4+ Th cells of the Th1 (predominantly IFNγ) and Th2 (predominantly IL-4) cells as well as CD8+ T cells have been shown to play a key role for an effective anti-tumor response." (PMID 24885059, 2014). "In preclinical models of murine lymphoma and Lewis lung carcinoma, IL-4 is shown to be a tumor growth supporting cytokine." (PMID 25208941, 2014). "IL-4 and TNFα can both be produced by different immune cells and thus represent components of the tumor microenvironment." (PMID 24885059, 2014). "In conclusion, the present pilot study revealed a significant correlation between three serological markers (osteopontin, IL-4 and IL-6) and a histopathologically confirmed neoplasm of the head and neck." (PMID 25120668, 2014). "In contrast to earlier reports, IL-4 can reduce tumor growth suggesting that the time point and local distribution of high IL-4 levels have an impact on RCC progression." (PMID 24885059, 2014).